GPX4 (glutathione peroxidase 4)
Diseases named in the same sentence as GPX4 in open-access papers (continued):
Sharing a sentence is not in itself a finding about the gene and the disease.
liver fibrosis (27 papers, 2021 to 2026). "The reduction of fatty acyls was accompanied by attenuated liver fibrosis and upregulated GPX4 expression." (PMID 40723896, 2025). "Recent studies have shown that traditional Chinese medicine berberine inhibits liver fibrosis by inducing ferroptosis in HSCs by inhibiting the SLC7A11/GPX4 axis." (PMID 40524220, 2025). "In this study, we found that Fx effectively ameliorated CCl4‐induced liver fibrosis by activating Nrf2/HO‐1/GPX4 expression in mice." (PMID 40654534, 2025). "The herbal decoction demonstrated anti-fibrotic effects in a rat model of hepatic fibrosis, potentially through activation of the Nrf2/GPX4 signaling pathway and suppression of ferroptosis." (PMID 40490825, 2025). "Based on the present study findings, Fx exerts antioxidant properties by upregulating the Nrf2 pathway and GPX4‐mediated ferroptosis to alleviate CCl4‐induced murine liver fibrosis." (PMID 40654534, 2025). "The present study aimed to demonstrate the therapeutic effect of Fx on CCl4‐induced hepatic fibrosis through the Nrf2/HO‐1/GPX4‐mediated ferroptosis pathway in vivo." (PMID 40654534, 2025). "GPX4, a classical inhibitor of ferroptosis, when down-regulated, can aggravate pulmonary fibrosis, liver fibrosis, and other fibrotic diseases by regulating autophagy, oxidative stress, and other pathways." (PMID 40442779, 2025). "The GSH, GPX4 and SLC7A11 expression were decreased and ferroptosis was activated in CCl4-induced liver fibrosis mice, but the GPX4 and SLC7A11 expression were increased and ferroptosis signature was attenuated in LX-2 cells treatment with LPS." (PMID 40278581, 2025). "Recent data showed that FUNDC1-mediated mitophagy led to ferroptosis and hepatic fibrosis by degrading glutathione peroxidase 4 (GPX4) in mitochondria, while knockdown of FUNDC1 ameliorated fibrosis." (PMID 39183973, 2024). "Fgfr3, Camk4, Gpx4, Hoxd3, and Prkcb were verified to be hyper-methylated in hepatic fibrosis of mice induced by CCl4 for 8 weeks." (PMID 36594057, 2023). "Obacunone is able to alleviate liver fibrosis by enhancing the antioxidant effects of glutathione peroxidase 4 (GPx-4) and inhibiting EMT." (PMID 35707473, 2022). "The objective of this study is to examine the mechanistic role of a TCM herbal decoction designed to promote Qi, blood circulation, and water excretion, in modulating the Nrf2/GPX4 signaling pathway and inhibiting ferroptosis in a rat model of hepatic fibrosis." (PMID 40490825, 2025). "The schaftoside isolated from 75% ethanol extracts of Clinacanthus nutans showed to hepatoprotective activities against CCl4-induced liver injuries in mice via amplifications of Nrf2 expression and triggered the Nrf2/GPX4 pathway to reduce oxidative stress levels and attenuate liver fibrosis." (PMID 41021178, 2025). "Furthermore, studies have shown that Ficus hirta Vahl (FV) can induce HSCs ferroptosis through the glutathione (GSH)/glutathione peroxidase 4 (GPX4) pathway to alleviate liver fibrosis in mouse models." (PMID 40568596, 2025). "This study indicates that Fx mitigates CCl4‐induced liver fibrosis in mice, likely via activation of the Nrf2/HO‐1/GPX4 axis and inhibition of ferroptosis, reflected by reduced hepatic iron overload, lipid peroxidation, and mitochondrial damage, alongside upregulated GPX4 expression." (PMID 40654534, 2025). "Ferroptosis regulatory pathways can be broadly classified into three groups: the glutathione/glutathione peroxidase 4 (GSH/GPX4), iron metabolism, and lipid metabolism pathways, and ferroptosis could induce liver fibrosis." (PMID 38755566, 2024). "These extracts administered to mice also inhibited ferroptosis in the liver by regulating the expression of Acyl-CoA synthetase long chain family member 4 (ACSL4), solute carrier family 7 member 11 (SLC7A11) and glutathione peroxidase 4 (GPX4), thus reducing the occurrence of liver fibrosis." (PMID 37032323, 2023). "Curcumol inhibits GPX4, thereby inducing HSCs ferroptosis to alleviate liver fibrosis." (PMID 36703745, 2022).
liver fibrosis (continued). "Thus, we demonstrate that obacunone is able to attenuate liver fibrosis via enhancing GPx-4 signal and inhibition of the TGF-β/P-Smad pathway and EMT process." (PMID 33435504, 2021). "Moreover, we found that lower ROS and degree of liver fibrosis with up-regulating expressions of Nrf-2 and GPx-4." (PMID 33435504, 2021). "So, we believe that Oba could relieve liver fibrosis by regulating the Nrf-2 and GPx-4." (PMID 33435504, 2021). "Isoliquiritigenin can inhibit the expression of GPX4 and increase the expression of TFR and divalent metal ion transporter 1, produce a large amount of ROS, induce HSCs ferroptosis, and alleviate liver fibrosis." (PMID 40524220, 2025). "Wogonoside activated ferroptosis by decreasing the levels of solute carrier family 7 member 11 (SLC7A11), GPX4, and GSH in mouse HSC-T6 cells, while reducing the levels of α-smooth muscle actin (α-SMA) with COL1A1 and alleviating liver fibrosis." (PMID 40278581, 2025). "ACSL4 was lowly expressed in the liver fibrosis model and we overexpressed ACSL4, ROS, Iron, MDA with elevated expression and GPX4, GSH with reduced expression." (PMID 40148434, 2025). "In a CCl4-induced liver fibrosis model, BECN1-containing exosomes promoted ferroptosis in HSCs by modulating the cystine/glutamate exchange transporter (xCT) and the glutathione peroxidase 4 (GPX4) enzyme." (PMID 40852596, 2025). "QG, the active ingredient of HGTLF, can induce ferroptosis of HSCs by targeting the degradation of GPX4 through ubiquitination and inhibit HSC activation, thereby alleviating liver fibrosis in NAFLD." (PMID 40524220, 2025). "Further, artesunate ultimately induces ferroptosis in HSCs and ameliorates liver fibrosis development by depleting glutathione (GSH), reducing glutathione peroxidase 4 (GPX4) activity, and favoring ROS accumulation." (PMID 37007035, 2023). "A recent study demonstrated that liraglutide can alleviate liver fibrosis by inhibiting hepatocyte ferroptosis through upregulating SLC7A11 expression and the Nrf2/HO-1/GPX4 pathway." (PMID 36703745, 2022). "Studies have shown that activation of ferroptosis in mouse HSCs using Erastin increased reactive oxygen species (ROS) and malondialdehyde (MDA) levels, decreased glutathione peroxidase 4 (GPX4), glutathione (GSH) and COL1A1 levels and alleviated liver fibrosis." (PMID 40278581, 2025). "Interestingly, Dan attenuated LPS‐induced liver fibrosis in those cells by upregulating collagen I, CTGF, Gpx4, and SLC7A11 and by increasing lipid reactive oxygen species accumulation." (PMID 36655094, 2023). "MSC-ex may promote xCT/GPX4 mediated HSCs ferroptosis through the delivery of BECN1 and highlights BECN1 as a potential biofactor for alleviating liver fibrosis." (PMID 35395830, 2022). "In addition, MSC-ex-derived BECN1 decreased xCT/GPX4 expression and inhibited HSCs activation, providing a novel insight into the proferroptosis effect of MSC-ex in liver fibrosis." (PMID 35395830, 2022). "However, no reports on the effect of Oba in liver fibrosis are reported, especially on GPx-4 mediating anti-phospholipid oxidation, TGF-β-Smad signals, and EMT process." (PMID 33435504, 2021).
neuroblastoma (27 papers, 2018 to 2025). Neuroblastoma (NB) is the most common solid, extracranial childhood tumor. "A better knowledge of the association between the GPX4 protein and neuroblastoma will assist solve medication resistance, high recurrence, and enhance neuroblastoma prognosis." (PMID 40969276, 2025). "For instance, tumor cells are more susceptible to GPX4 inhibitors in the therapy of neuroblastoma because of the high expression of the tumor’s own MYCN gene." (PMID 40969276, 2025). "Recently, we, and others, have uncovered that high‐risk MYCN‐amplified neuroblastomas are characterized by a striking GPX4 dependency." (PMID 37435859, 2023). "In vitro, Sch B suppresses erastin-induced ferroptosis in SH-SY5Y neuroblastoma cells by modulating the GSK3β/Nrf2/GPX4 signaling pathway." (PMID 40661149, 2025). "pharmacological blocking of cystine transport, transsulfuration, and GPX4 inactivation led to tumour regression in a MYCN‐amplified neuroblastoma model." (PMID 39095325, 2024). "Withaferin A, a naturally occurring ferroptosis inducer, inhibits the growth of xenoblastoma and dose-dependently inactivates GPX4 in neuroblastoma." (PMID 37598126, 2023). "Pharmacological inhibition of both cystine uptake and transsulfuration combined with GPX4 inactivation resulted in tumor remission in an orthotopic MYCN-amplified neuroblastoma model." (PMID 35484422, 2022). "Combined targeting of cystine uptake, cysteine synthesis via transsulfuration and GPX4 in an orthotopic neuroblastoma model strongly reduced tumor growth in vivo." (PMID 35484422, 2022). "We then generated an orthotopic mouse model for human neuroblastoma by transplanting these SK-N-DZ neuroblastoma cells orthotopically into the adrenal gland and allow the cells expressing native GPX4 levels to develop into small tumors." (PMID 35484422, 2022). "Using functional MYCN synthetic lethal metabolic and genetic screens, we further identified cyst(e)ine deprivation and glutathione peroxidase 4 (GPX4) inhibition as selective liabilities in MYCN-amplified neuroblastomas." (PMID 35484422, 2022). "In the meantime, decrease of GPX4 expression by the natural compound withaferin A was also previously found to trigger ferroptotic death in neuroblastoma cells." (PMID 33969928, 2021). "Further studies revealed that the transferrin receptor 1 was upregulated in response to such MYCN amplification, leading to increased GPx4 sensitivity and rendering neuroblastoma cells vulnerable to ferroptosis induction." (PMID 34926298, 2021). "Administration of withaferin A significantly suppressed the tumor growth of neuroblastoma through increased HO-1 expression and decreased GPx4 expression." (PMID 30583467, 2018). "Furthermore, inducible ablation of GPX4 in vivo suppressed the growth of MYCN‐amplified neuroblastomas." (PMID 35908258, 2022). "GPX4 dependency in cancer cell lines was associated with enhanced expression of cystathionine beta-synthase (CBS), the rate-limiting enzyme for transsulfuration, with neuroblastoma being among the cancer entities with the highest CBS expression." (PMID 35484422, 2022). "Recently, treatment with the steroidal lactone withaferin A was found to induce the nuclear factor erythroid 2–related factor 2 (Nrf2) pathway and to inactivate the GPx4 pathway, a duality making this strategy highly effective in treating both neuroblastoma cells and transplanted xenografts in mice." (PMID 34926298, 2021). "We found that neuroblastoma expresses a similar amount of Gpx4 as most other cancer cell lines." (PMID 34445601, 2021). "GPX4 protein could be a good target for neuroblastoma drugs." (PMID 40969276, 2025). "In neuroblastoma, elevated expression of MYCN, a member of the MYC family, can increase lipid peroxidation and promote ferroptosis, a process that may be associated with the use of GPX4 inhibitors." (PMID 39039611, 2024).
neuroblastoma (continued). "Considering that GPX4 is an essential gene in many cancer cell lines, it will be important to assess whether GPX4 ablation also affects the growth of corresponding MYCN‐low neuroblastomas (and therefore whether GPX4 inactivation would selectively impair MYCN‐high tumour growth)." (PMID 35908258, 2022). "In vitro, myricetin treatment of SH-SY5Y neuroblastoma cells exposed to 1-methyl-4-phenylpyridine (MPP+) significantly reduces Fe2+ and ROS levels, activates the NRF2/GPX4 signaling pathway, suppresses neuronal ferroptosis, and mitigates cellular injury." (PMID 40661149, 2025). "Mouse embryonic fibroblasts NIH3T3, human fibrosarcoma cells HT1080, human neuroblastoma SH-SY5Y, mouse embryonic fibroblasts Pfa1, and mouse hippocampal neuronal HT22 cells were treated with a covalent inhibitor of GPx4 (RSL3) to induce ferroptosis." (PMID 41315180, 2025). "Our data demonstrate that targeting SELENOP uptake via LRP8 is a valuable strategy to efficiently disrupt GPX4 maintenance and trigger ferroptosis in cultured MYCN‐amplified neuroblastoma cells." (PMID 37435859, 2023). "In summary, our data show that GPX4 partially protects high MYCN neuroblastoma cells from ferroptosis in vitro and in an orthotopic neuroblastoma mouse model." (PMID 35484422, 2022). "Cumulatively, their data support a triple combination therapy by inhibiting GPX4, cystine uptake and cysteine synthesis to eliminate MYCN‐amplified neuroblastomas." (PMID 35908258, 2022). "Furthermore, withaferin A promotes neuroblastoma (NB) cell death by increasing LIP levels through Hmox1, in addition to inactivating GPX4." (PMID 38267442, 2024). "The present study demonstrates that blocking selenium/selenocysteine uptake mechanisms could be an attractive indirect strategy to disrupt GPX4 function specifically and selectively to induce ferroptotic cell death in MYCN‐amplified neuroblastoma." (PMID 37435859, 2023). "Thus, LRP8 blockade represents a rational strategy to indirectly deplete GPX4 and selectively trigger ferroptosis in MYCN‐amplified neuroblastoma and potentially other entities with low system Xc− expression/activity such as AML and lymphoma, while sparring normal cells." (PMID 37435859, 2023). "Presumably differentiated neuroblastoma cell lines are more sensitive to RSL3 treatment (i.e., GPX4 inhibition) rather than erastin (the system xc- inhibitor) because these cells already have higher basal levels of cysteine due to the upregulation of SLC7A11 during the differentiation process." (PMID 39329725, 2024). "Publicly available data (depmap portal) indicate that in neuroblastomas, LRP8 dependency is inversely correlated with SLC7A11 expression with LRP8 knockout sensitive cell lines exhibiting lower SLC7A11 expression levels, while this is not observed for GPX4." (PMID 37435859, 2023).
Obesity (27 papers, 2017 to 2026). Accumulation of substantial excess body fat. "Together, these results suggest that loss of Gpx4 in macrophages mitigates obesity‐associated inflammation, potentially through ferroptosis‐mediated depletion or functional reprogramming of inflammatory macrophages." (PMID 41524084, 2026). "Collectively, these findings suggest that macrophage‐specific Gpx4 deficiency mitigates diet‐induced obesity in mice in vivo." (PMID 41524084, 2026). "These beneficial metabolic effects seemed to be associated with enhanced macrophage ferroptosis, suggesting a mechanistic link between Gpx4 deficiency, ferroptosis, and the alleviation of obesity‐associated insulin resistance." (PMID 41524084, 2026). "While prior studies have linked Gpx4 deletion in neurons and adipocytes to worsened metabolic outcomes, our findings reveal that loss of GPX4 in macrophages produces the opposite effect—attenuating obesity, dyslipidemia, and insulin resistance." (PMID 41524084, 2026). "Ferroptosis is intricately linked to obesity, and it is characterized by iron buildup, lipid peroxide hyperplasia, GPX4 inhibition, and systemic Xc inhibition in the adipose tissue under obesity conditions." (PMID 40216765, 2025). "Epidemiological studies have found that human GPX4 gene variants are associated with obesity and cardiovascular diseases." (PMID 39396974, 2024). "In relation to obesity, genetic variants in GPX4 have been linked to obesity and inflammation in humans, suggesting a role for GPX4 in metabolic disorders." (PMID 36479119, 2022). "While the GPX gene cluster includes eight types (GPX1-8), the GPX1 and GPX4 variants were associated previously with obesity or related comorbidities." (PMID 33924357, 2021). "In conclusion, prepregnancy obesity is associated with a decrease in GPx4 expression in the placenta, which is related to OS in the newborn." (PMID 31312657, 2019). "Prepregnancy obesity is associated with a decrease in GPx4 expression in the placenta, which is related to OS in the newborn." (PMID 31312657, 2019). "Too much data regarding the association between obesity and GPx1, GPx3, GPx4, and GPx7 has been reported." (PMID 29132311, 2017). "Because obesity and insulin resistance are commonly associated with hepatic steatosis, we investigated whether macrophage‐specific Gpx4 deletion affects hepatic lipid metabolism." (PMID 41524084, 2026). "Emerging evidence has shown that GPX4 expression is reduced in macrophages under hyperglycemic conditions; however, the involvement of macrophage‐specific GPX4 in obesity‐associated insulin resistance remains unclear." (PMID 41524084, 2026). "The antioxidant Gpx4 effectively hinders the production of ROS caused by oxidative stress in adipose tissue, thereby mitigating adipose inflammation through the prevention of lipid peroxidation in obesity." (PMID 38068762, 2023). "Prepregnancy obesity was associated with a decreased placental expression of GPx4." (PMID 31312657, 2019). "To investigate the role of macrophage GPX4 in obesity‐induced insulin resistance, we generated Gpx4Mac‐KO mice by crossbreeding Gpx4fl/fl mice with Lyz2‐Cre mice." (PMID 41524084, 2026). "To investigate the role of macrophage Gpx4 in obesity related insulin resistance, we performed glucose tolerance tests (GTT) and insulin tolerance tests (ITT) in chow‐ and HFD‐fed Gpx4fl/fl and Gpx4Mac‐KO mice." (PMID 41524084, 2026). "Since GPX4 is a key regulator of ferroptosis, we finally investigated whether Gpx4 deficiency‐mediated ferroptosis in macrophages is involved in the development of obesity‐associated insulin resistance by performing transcriptomic analysis on BMDMs derived from Gpx4Mac‐KO and Gpx4fl/fl mice." (PMID 41524084, 2026). "Macrophage‐specific loss of Gpx4 induces ferroptosis, thereby alleviating high‐fat diet (HFD)‐induced obesity, insulin resistance, and metabolic dysfunction, and conferring systemic metabolic protection in type 2 diabetes (T2D)." (PMID 41524084, 2026).